LINC01705 (long independently transcribed non-coding RNA 1705)
Synonyms: ERLR; TBUR1; RP11-400N13.3; LINC02257; formerly LINC01655
Gene: Long non-coding RNA gene on chromosome 1 (221,811,869 to 222,064,817, reverse strand). Ensembl gene ENSG00000232679.
Diseases named in the same sentence as LINC01705 in open-access papers:
LINC01705 is named in the same sentence as 10 diseases in open-access papers, as found by Europe PMC text mining. Sharing a sentence is not in itself a finding about the gene and the disease. The quoted sentences say what the papers report.
breast carcinoma (6 papers, 2020 to 2025). "In conclusion, our results suggest that LINC01705 is implicated in the progression of breast cancer via competitively binding to miR-186-5p as a competing endogenous RNA (ceRNA), thereby regulating TPR expression." (PMID 32849791, 2020). "Collectively, this study confirmed that LINC01705 is implicated in the progress of breast cancer via sponging miR-186-5p, thereby mediating the expression of the TPR, providing a novel perspective for the study of the pathogenesis of breast cancer." (PMID 32849791, 2020). "Thus, both LINC01705 and miR-186-5p are implicated in the development and progression of breast cancer." (PMID 32849791, 2020). "The proliferation of breast cancer cells was notably reduced by downregulation of LINC01705 and enhanced by overexpression of LINC01705, as shown by the CCK-8 assay." (PMID 32849791, 2020). "Then, qRT-PCR was conducted to detect LINC01705 expression in breast cancer cells (MCF-7, CAL-51, BT-20, BT-549, and AU565) and human normal mammary epithelial cells MCF 10A; high expression of LINC01705 was observed in breast cancer cells." (PMID 32849791, 2020). "qRT-PCR was used to verify the transfection efficacy of the sh-LINC01705 and LINC01705 overexpression vectors in breast cancer cells." (PMID 32849791, 2020). "A prominent elevation of LINC01705 expression was identified in breast cancer tissues relative to adjacent tissues." (PMID 32849791, 2020). "Our results revealed overexpression of LINC01705 in breast cancer cells and tissues, and overexpression of LINC01705 promoted the proliferation and migration of BT-549 and MCF-7 cells." (PMID 32849791, 2020). "This suggests that LINC01705 is involved in the progression of breast cancer via post-transcriptional regulation." (PMID 32849791, 2020). "LINC01705 positively regulates the translocation promoter region nuclear basket protein by competitively binding to miR-186-5p, thereby promoting the aggressiveness of breast cancer cells." (PMID 35237306, 2022). "Moreover, downregulation of LINC01705 decreased cell cycle progression, proliferation, invasion, and migration in breast cancer, indicating that LINC01705 is a key regulatory factor in breast cancer cell growth as a carcinogene." (PMID 32849791, 2020). "Overexpression of LINC01705 notably enhanced cell migration and proliferation in breast cancer." (PMID 32849791, 2020). "Microarray analysis has unveiled elevated LINC01705 expression in breast cancer." (PMID 32849791, 2020). "In addition, the invasion experiment showed that breast cancer cell invasion was decreased by downregulation of LINC01705 and enhanced by overexpression of LINC01705." (PMID 32849791, 2020). "In addition, based on the wound-healing assay, breast cancer cell migration was decreased by downregulation of LINC01705 and enhanced by overexpression of LINC01705." (PMID 32849791, 2020). "We found that LINC01705 is significant overexpression in breast cancer samples." (PMID 32849791, 2020). "The results demonstrated that breast cancer patients with increased levels of AC009686.2, AC132807.2, AC093515.1, AC129926.2, AL513123.1, RHPN1-AS1, KCNMB2-AS1, LINC01614, LINC01705, and C6orf99 had a better overall survival." (PMID 37884650, 2023). "In summary, LINC01705 acts as a competitive endogenous RNA to regulate TPR expression via sponging miR-186-5p, thereby regulating the progression of breast cancer." (PMID 32849791, 2020). "Our findings revealed high LINC01705 expression in breast cancer tissues relative to adjacent non-cancerous tissues (n = 40, P < 0.001)." (PMID 32849791, 2020).
Cluster headache (2 papers, 2022 to 2025). A type of headache characterized by repeated attacks of unilateral pain lasting 15 to 180 minutes and associated with local autonomic signs. "The four cluster headache susceptibility loci that were identified by this GWAS were rs113658130 near LINC01877/SATB2 (SATB homeobox 2), rs4519530 in MERTK, rs12121134 near LINC01705/DUSP10 (Dual Specificity Phosphatase 10), and rs11153082 in FHL5." (PMID 39560176, 2025). "Moreover, we found evidence of suggestive association among previously suggested loci to be involved in cluster headache, including LINC01877, LINC01705, ADCYAP1R1, and MME." (PMID 36404298, 2022).
keloid (1 paper, 2025). An irregularly shaped, elevated mark on the skin caused by deposits of excessive amounts of collagen during wound healing. "The top result was for LINC01705; increased predicted expression of LINC01705 in fibroblasts was associated with decreased risk of keloids (p = 1.10 × 10-20, OR = 0.65 [0.59 – 0.71])." (PMID 40835838, 2025).
osteosarcoma (1 paper, 2022). A usually aggressive malignant bone-forming mesenchymal neoplasm, predominantly affecting adolescents and young adults. "Moreover, miR-223-5p-LINC01705 is involved in pulmonary metastasis of osteosarcoma as a microRNA–lncRNA target pair." (PMID 35237306, 2022).
proliferative vitreoretinopathy (1 paper, 2022). Vitreoretinal membrane shrinkage or contraction secondary to the proliferation of primarily retinal pigment epithelial cells and glial cells, particularly fibrous astrocytes, followed by membrane formation. "In addition, LINC01705 has high expression during the pathogenesis of proliferative vitreoretinopathy." (PMID 35237306, 2022).
LINC01705 also shares sentences with these, for which no sentence is quoted: tumor (8 papers); cancer (7); colorectal cancer (5); colon cancer (4); colon adenocarcinoma (1).